TMEM204 (transmembrane protein 204)
Description:
Can influence paracellular permeability. Appears to be involved in cell-cell interactions through adherens.
Synonyms: C16orf30; CLP24; FLJ20898
Tractability: Antibody: UniProt places it where antibodies can reach, with high confidence; UniProt predicts a signal peptide or a membrane-spanning region; its Gene Ontology location is reachable by antibodies, with medium confidence.
Gene: Protein-coding gene on chromosome 16 (1,528,688 to 1,555,580, forward strand). Ensembl gene ENSG00000131634.
Subcellular location: Cell junction, adherens junction; Cell membrane
Gene Ontology:
Biological process: lymph vessel development; regulation of vascular endothelial growth factor receptor signaling pathway; smooth muscle cell differentiation
Cellular component: plasma membrane; adherens junction
Genetic constraint (gnomAD): Loss-of-function variants: 15 observed, 18.68 expected, observed/expected ratio (o/e) 0.8, 90% interval 0.54 to 1.24. The upper end of that interval is the gene's LOEUF score, 1.24, which puts it in group 5 of 6, group 1 being the genes least tolerant of losing a copy. Missense variants: 287 observed, 320.97 expected, observed/expected ratio (o/e) 0.89, 90% interval 0.81 to 0.99. Synonymous variants: 161 observed, 148.93 expected, observed/expected ratio (o/e) 1.08, 90% interval 0.95 to 1.23.
Homologues: Orthologues: macaque TMEM204 (98% identical), pig TMEM204 (89% identical), rat Tmem204 (89% identical), guinea pig TMEM204 (88% identical), mouse Tmem204 (88% identical), chimpanzee TMEM204 (78% identical), tropical clawed frog tmem204 (75% identical), dog TMEM204 (66% identical), zebrafish tmem204 (66% identical), rabbit TMEM204 (61% identical).
Diseases named in the same sentence as TMEM204 in open-access papers:
TMEM204 is named in the same sentence as 5 diseases in open-access papers, as found by Europe PMC text mining. Sharing a sentence is not in itself a finding about the gene and the disease. The quoted sentences say what the papers report.
diabetes (1 paper, 2025). "A transmembrane protein gene, TMEM204, typically hypomethylated in MASLD patients, was found to be hypermethylated, and EFCAB11, often downregulated in obese individuals with diabetes, showed similar hypermethylation in prenatal-BPA treated liver samples." (PMID 40914344, 2025).
cancer (1 paper, 2011). A tumor composed of atypical neoplastic, often pleomorphic cells that invade other tissues. "Also, some new cancer-specific genes are found, such as TMEM204, which has the highest weight for GIST, 0.96; when looking at GeneSapiens data, the gene's expression is shown to be extremely specific to GIST." (PMID 21955394, 2011).
tumor (1 paper, 2023). "In the tumor microenvironment, the up-regulation of three TMEM genes (TMEM204, TMEM88, and TMEM59) in endothelial cells caught our attention." (PMID 37265785, 2023).
TMEM204 also shares sentences with these, for which no sentence is quoted: orofacial cleft (1 paper); retinitis pigmentosa (1).